SLC30A5 (solute carrier family 30 member 5)
Description:
Together with SLC30A6 forms a functional proton-coupled zinc ion antiporter mediating zinc entry into the lumen of organelles along the secretory pathway. By contributing to zinc ion homeostasis within the early secretory pathway, regulates the activation and folding of enzymes like alkaline phosphatases and enzymes involved in phosphatidylinositol glycan anchor biosynthesis. Through the transport of zinc into secretory granules of pancreatic beta-cells, plays an important role in the storage and secretion of insulin. [Isoform 2]: Zinc ion:proton antiporter mediating influx and efflux of zinc at the plasma membrane.
Synonyms: ZnT-5; ZNT5; ZNTL1; ZTL1; FLJ12496; FLJ12756; MGC5499
Tractability: Antibody: UniProt places it where antibodies can reach, with high confidence; its Gene Ontology location is reachable by antibodies, with high confidence; UniProt predicts a signal peptide or a membrane-spanning region. PROTAC: ubiquitination databases record sites on it; its protein half-life has been measured.
Gene: Protein-coding gene on chromosome 5 (69,093,991 to 69,131,069, forward strand). Ensembl gene ENSG00000145740.
Subcellular location: Golgi apparatus, Golgi stack membrane; Cytoplasmic vesicle, COPII-coated vesicle membrane; Cytoplasmic vesicle, secretory vesicle membrane; Golgi apparatus, trans-Golgi network membrane; Lateral cell membrane; Cytoplasm; Endoplasmic reticulum membrane (Isoform 2); Cell membrane; Apical cell membrane
Subcellular location (Human Protein Atlas): Golgi apparatus; Nucleoplasm
Pathways (Reactome):
Metabolism of proteins: Insulin processing
Transport of small molecules: Zinc efflux and compartmentalization by the SLC30 family
Gene Ontology:
Molecular function: protein binding; zinc ion transmembrane transporter activity; zinc:proton antiporter activity; monoatomic cation transmembrane transporter activity
Biological process: cobalt ion transport; GPI anchor biosynthetic process; zinc ion import into Golgi lumen; zinc ion import into organelle; zinc ion transport; insulin processing; intracellular zinc ion homeostasis; zinc ion transmembrane transport; monoatomic cation transport; transmembrane transport
Cellular component: apical plasma membrane; endoplasmic reticulum membrane; ER to Golgi transport vesicle membrane; Golgi apparatus; Golgi cis cisterna membrane; Golgi membrane; membrane; plasma membrane; secretory granule; secretory granule membrane; transmembrane transporter complex; cytoplasmic vesicle; lateral plasma membrane; cytoplasm; Golgi cisterna membrane; transport vesicle membrane
Genetic constraint (gnomAD): Loss-of-function variants: 21 observed, 44.9 expected, observed/expected ratio (o/e) 0.47, 90% interval 0.33 to 0.67. The upper end of that interval is the gene's LOEUF score, 0.67, which puts it in group 2 of 6, group 1 being the genes least tolerant of losing a copy. Missense variants: 600 observed, 715.66 expected, observed/expected ratio (o/e) 0.84, 90% interval 0.78 to 0.9. Synonymous variants: 236 observed, 252.44 expected, observed/expected ratio (o/e) 0.93, 90% interval 0.84 to 1.04.
Homologues: Orthologues: chimpanzee SLC30A5 (99% identical), macaque SLC30A5 (99% identical), dog SLC30A5 (98% identical), pig SLC30A5 (97% identical), rabbit SLC30A5 (97% identical), guinea pig SLC30A5 (96% identical), mouse Slc30a5 (95% identical), rat Slc30a5 (94% identical), zebrafish slc30a5 (78% identical), tropical clawed frog slc30a5 (77% identical), Caenorhabditis elegans slc-30A5 (40% identical). Paralogues in human: SLC30A7 (21% identical), SLC30A10 (13% identical), SLC30A1 (13% identical), SLC30A4 (11% identical), SLC30A2 (10% identical), SLC30A6 (10% identical), SLC30A8 (9% identical), SLC30A3 (9% identical).
Diseases named in the same sentence as SLC30A5 in open-access papers:
SLC30A5 is named in the same sentence as 34 diseases in open-access papers, as found by Europe PMC text mining. Sharing a sentence is not in itself a finding about the gene and the disease. The quoted sentences say what the papers report.
prostate carcinoma (5 papers, 2018 to 2025). A carcinoma that arises from epithelial cells of the prostate gland. "LocusZoom plots were generated for each SNP that significantly contributed to the positive association between gout and prostate cancer, and each SNP was assigned to the closest gene: SLC30A5 (rs2560449), IL1R1 (rs17767183), IL1RN (rs9973741)." (PMID 40385401, 2025). "Additionally, depleted zinc concentration is associated with prostate cancer progression, and zinc transporter SLC30A5 has been shown to be downregulated in cancerous tissue." (PMID 40385401, 2025). "Based on the Oncomine database records, the expression of Zn-exporter genes SLC30A1, SLC30A9, and SLC30A10 are upregulated, and SLC30A5 and SLC30A6 are downregulated in prostate cancer compared to BPH." (PMID 36551962, 2022). "Our MR study identified three genes driving the relationship between the non-hyperuricemia compartment of gout and prostate cancer: IL1R1 (rs17767183), IL1RN (rs9973741), and SLC30A5 (rs2560449)." (PMID 40385401, 2025).
Osteopenia (4 papers, 2010 to 2025). Osteopenia is a term to define bone density that is not normal but also not as low as osteoporosis. "Notably, previous studies demonstrated osteopenia and male‐specific cardiac death in mice lacking the ZnT5/SLC30A5 zinc transporter, and suggested association of two homozygous frameshift SLC30A5 variants with perinatal mortality in humans, due to hydrops fetalis and hypertrophic cardiomyopathy." (PMID 39790720, 2025).
cardiomyopathy (3 papers, 2021 to 2025). A disease of the heart muscle or myocardium proper. "Here we describe four individuals in two unrelated consanguineous families with lethal cardiomyopathy, arrhythmia, and hydrops fetalis/cystic hygroma in whom we identified homozygous variants in SLC30A5." (PMID 33547425, 2021). "Similarly, previously‐reported human individuals homozygous for SLC30A5 biallelic truncation variants (p.(Ile278Phefs*33) and p.(His661Tyrfs*10), NM_022902.4), putatively causing loss of function, presented with cardiomyopathy and perinatal death." (PMID 39790720, 2025). "Interestingly, pathological variants of SLC30A5 that cause homozygous loss of function have been shown to cause cardiomyopathy and perinatal death, similar with what has been reported for ZnT5 KO mice." (PMID 35745255, 2022). "Taken together, we present SLC30A5 as a new gene for a severe and perinatally lethal form of cardiomyopathy." (PMID 33547425, 2021).
colorectal cancer (2 papers, 2020 to 2025). A primary or metastatic malignant neoplasm that affects the colon or rectum. "SLC30A5-7 and 9 are significantly upregulated in colorectal cancer and SLC30A9 is involved in the canonical Wnt pathway." (PMID 33110097, 2020).
cystic hygroma (2 papers, 2021 to 2025). A benign lymphatic neoplasm usually arising from the neck and characterized by cystic dilation of the lymphatic vessels. "In contrast to the four previously reported cases with SLC30A5 variants, our patients did not present with hydrops fetalis/cystic hygroma or any evident cardiac phenotype, yet had severe neurological manifestations." (PMID 39790720, 2025).
gastric cancer (2 papers, 2020 to 2022). A primary or metastatic malignant neoplasm involving the stomach. "In the present study, mRNA expression of SLC30A1-3, SLC30A5-7, and 9 was significantly upregulated in gastric cancer tissues compared to non-cancer tissues in GC patients, while SLC30A4 was downregulated in cancer tissues." (PMID 33110097, 2020).
cervical cancer (1 paper, 2022). A primary or metastatic malignant neoplasm involving the cervix. "For tumor stages, SLC30A1, SLC30A7 and SLC30A10 groups significantly varied, whereas SLC30A2, SLC30A3, SLC30A4, SLC30A5, SLC30A6, SLC30A8 and SLC30A9 did not significantly differ in cervical carcinoma." (PMID 35154468, 2022). "However, the expression of SLC30A3, SLC30A4, SLC30A5, SLC30A6 and SLC30A9 genes in cervical cancer was not statistically significant compared to the corresponding paracancerous tissues." (PMID 35154468, 2022).
Failure to thrive (1 paper, 2025). Failure to thrive (FTT) refers to a child whose physical growth is substantially below the norm. "Thus, a biallelic variant in SLC30A5 (ZnT5), affecting cytosolic zinc concentrations, causes a severe hypotonia syndrome with respiratory insufficiency and failure to thrive, lethal by 1 year of age." (PMID 39790720, 2025).
gastric adenocarcinoma (1 paper, 2023). "In addition, we found that the expression levels of SLC30A1, SLC30A5, SLC30A6 and SLC30A7 were significantly elevated, while the expression level of SLC30A4 was significantly decreased in gastric adenocarcinoma tissues compared with both normal gastric tissues and matched normal gastric tissues." (PMID 37524874, 2023).
hepatocellular carcinoma (1 paper, 2024). A malignant tumor that arises from hepatocytes. "This study aimed to explore the expression and prognostic significance of SLC30A family genes in pan-cancer, with a specific emphasis on SLC30A5 in hepatocellular carcinoma (HCC)." (PMID 39006068, 2024).
hyperuricemia (1 paper, 2025). An abnormally high level of uric acid. "Loci contributing most strongly to the non-hyperuricemia causal effect included three genes: IL1R1, IL1RN, and SLC30A5." (PMID 40385401, 2025).
tumor (6 papers, 2011 to 2024). "Co-expression analysis explored the relationship between SLC30A5 and immune cell infiltration, immune checkpoints, pathway molecules related to tumor angiogenesis and epithelial-mesenchymal transition (EMT)." (PMID 39006068, 2024). "Meanwhile, SLC30A1-7, and 9 were significantly correlated with advanced tumor stage and nodal metastasis status, SLC30A5-7, and 9–10 were significantly related to the Helicobacter pylori infection status of GC patients." (PMID 33110097, 2020). "Retroviral insertions were present in the mouse homologs of 10 genes tagged in the zebrafish tumor samples: Brd2, Cirbp, Fgf8, Hexim1, Map2k5, Mmp14, Ncoa2, Slc30a5, Sox4, and Sox5." (PMID 21533036, 2011). "The differential expression of SLC30A1, SLC30A5, SLC30A6, SLC30A9 and SLC30A10 was found to vary with tumor stage and grade and appears to be related mostly to early events in PCa development and progression." (PMID 27833104, 2016).
SLC30A5 also shares sentences with these, for which no sentence is quoted: cancer (3 papers); Obesity (3); Arrhythmia (2); breast carcinoma (2); diabetes (2); hydrops fetalis (2); type 2 diabetes mellitus (2); Zinc deficiency (2); Alzheimer disease (1); bacterial infection (1); cardiac arrhythmia (1); dystonia 1 (1); gout (1); heart failure (1); hypertrophic cardiomyopathy (1); Hypotonia (1); lymphoma (1); major depressive disorder (1); melanoma (1); respiratory failure (1); Respiratory insufficiency (1); Virus infection (1).